TCAP (titin-cap)
Description:
Muscle assembly regulating factor. Mediates the antiparallel assembly of titin (TTN) molecules at the sarcomeric Z-disk.
Synonyms: T-cap; TELE; telethonin; CMD1N; CMH25; LGMD2G; LGMDR7
Tractability: No criterion of Open Targets' tractability assessment is met for any kind of drug.
Gene: Protein-coding gene on chromosome 17 (39,665,349 to 39,666,554, forward strand). Ensembl gene ENSG00000173991.
Subcellular location: Cytoplasm, myofibril, sarcomere
Pathways (Reactome):
Muscle contraction: Striated Muscle Contraction
Gene Ontology:
Molecular function: BMP binding; FATZ binding; molecular adaptor activity; protein binding; protein-macromolecule adaptor activity; structural constituent of muscle; titin binding; titin Z domain binding; transmembrane transporter binding
Biological process: adult heart development; cardiac muscle cell development; cardiac muscle contraction; cardiac muscle hypertrophy; cardiac muscle hypertrophy in response to stress; cardiac muscle tissue morphogenesis; cardiac myofibril assembly; detection of muscle stretch; sarcomere organization; sarcomerogenesis; skeletal muscle contraction; skeletal muscle myosin thick filament assembly; skeletal muscle thin filament assembly; detection of mechanical stimulus; muscle filament sliding; protein-containing complex assembly; response to muscle stretch; anatomical structure formation involved in morphogenesis; animal organ morphogenesis; otic vesicle formation; somitogenesis; tissue morphogenesis
Cellular component: titin-telethonin complex; Z disc; cytosol; I band; sarcomere
Genetic constraint (gnomAD): Loss-of-function variants: 14 observed, 15.92 expected, observed/expected ratio (o/e) 0.88, 90% interval 0.58 to 1.37. The upper end of that interval is the gene's LOEUF score, 1.37, which puts it in group 5 of 6, group 1 being the genes least tolerant of losing a copy. Missense variants: 212 observed, 226.23 expected, observed/expected ratio (o/e) 0.94, 90% interval 0.84 to 1.05. Synonymous variants: 97 observed, 93.88 expected, observed/expected ratio (o/e) 1.03, 90% interval 0.88 to 1.22.
Gene-disease validity (ClinGen):
ClinGen rates the evidence that TCAP causes each of these diseases.
autosomal recessive limb-girdle muscular dystrophy (autosomal recessive): Definitive. Autosomal recessive form of limb-girdle muscular dystrophy.
dilated cardiomyopathy (autosomal dominant): Limited. Cardiomyopathy which is characterized by dilation and contractile dysfunction of the left and right ventricles.
hypertrophic cardiomyopathy (autosomal dominant): Disputed. A condition in which the myocardium is hypertrophied without an obvious cause.
Homologues: Orthologues: chimpanzee TCAP (99% identical), dog TCAP (90% identical), mouse Tcap (90% identical), rat Tcap (89% identical), guinea pig TCAP (88% identical), pig TCAP (77% identical), rabbit TCAP (72% identical), tropical clawed frog tcap (50% identical), zebrafish tcap (40% identical).
Diseases named in the same sentence as TCAP in open-access papers:
TCAP is named in the same sentence as 46 diseases in open-access papers, as found by Europe PMC text mining. Sharing a sentence is not in itself a finding about the gene and the disease. The quoted sentences say what the papers report.
cardiomyopathy (12 papers, 2011 to 2025). A disease of the heart muscle or myocardium proper. "Variants in the TCAP gene that have been previously reported in individuals with myopathy or cardiomyopathy." (PMID 33802723, 2021). "Gene TCAP is the causative gene of cardiomyopathy, hypertrophic, 25 (#607487)." (PMID 35910219, 2022). "Previous studies on the TCAP gene (telethonin protein) suggested that this gene may be a rare cause of cardiomyopathies among the other involving genes, even though dysfunctional telethonin interferes organizing of the structure of sarcomere assembly and regulates the sarcomere length." (PMID 37752589, 2023). "Our study, for the first time, showed that knockdown of TCAP recapitulates the phenotypes of cardiomyopathies in human iPSC-induced cardiomyocytes." (PMID 40969822, 2025). "To investigate the effect of TCAP on cardiomyopathy, we knocked down TCAP from the WT- iPSCs using CRISPR-Cas9 gene editing techniques." (PMID 40969822, 2025). "There is an increased prevalence of rare variants (BAG3, LMNA, MYH7, TCAP, TNNT2, and TTN), particularly TTNtv, in adult and pediatric cancer patients with cancer therapy-induced cardiomyopathy." (PMID 39070560, 2024). "This study was the first investigation on the TCAP gene among the Iranian cardiomyopathies population wherein the TCAP gene was analyzed in 40 unrelated patients (17 females and 23 males) who were clinically diagnosed with HCM and DCM." (PMID 37752589, 2023). "In summary, TCAP variants have been associated with both DCM and HCM, but further insights at cellular level are needed to understand the mechanism by which TCAP variants cause cardiomyopathies." (PMID 36935760, 2023). "Besides the hub genes of MYBPC3, MYH7, and DSP, these subnetworks also include several genes that have been implicated in cardiomyopathy, such as TPM1, ACTC1, DES, TCAP, JUP, and DSG2." (PMID 32344918, 2020). "Cardiomyopathy genes, including nine prespecified DCM genes including BCL2-associated athanogene-3 (BAG3), desmoplakin (DSP), LMNA, MYH7, sodium voltage-gated channel, alpha subunit 5 (SCN5A), telethonin (TCAP), cardiac troponin C (TNNC1), TNNT2, and TTN, were sequenced." (PMID 40004816, 2025). "Based on gene expression and histology, clusters 0, 2, and 4 are skeletal muscle due to the high expression of APOD, MB, TCAP, and TNNC2 with significant upregulation of contractile components and cardiomyopathy processes." (PMID 37370820, 2023).
dilated cardiomyopathy (10 papers, 2014 to 2024). "TCAP is also a sarcomeric protein whose mutations have been found in patients with HCM and dilated cardiomyopathy (DCM)." (PMID 38780967, 2024). "In this study, we investigate the frequency, clinical phenotypes, and spectrum of TCAP genetic variants in a cohort of hypertrophic cardiomyopathy (HCM) and dilated cardiomyopathy (DCM) patients referring to our tertiary center in Tehran." (PMID 37752589, 2023). "TCAP partially regulates prohypertrophic BMP10, thereby pathogenic variants in the BMP10 gene deter binding to TCAP and increase dilated cardiomyopathy occurrence." (PMID 37752589, 2023). "TCAP is required for sarcomerogenesis in striated muscles, and mutations in TCAP have been identified in patients with HCM and dilated cardiomyopathy (DCM)." (PMID 32344918, 2020). "Although patients with CCM had rare variants in several established dilated cardiomyopathy (DCM) genes (BAG3, LMNA, MYH7, TCAP, TNNT2, and TTN), only variants in TTN, which encodes titin, were significantly increased." (PMID 30987448, 2019). "In support of this notion, genetic ablation of TCAP in mice altered t-tubules and led to contractile and stretch-sensing defects, and defects in TCAP Z disc complexes with muscle LIM protein were associated with dilated cardiomyopathy and heart failure in humans." (PMID 25121604, 2014).
breast carcinoma (7 papers, 2006 to 2020). "GRB7, PNMT, and TCAP are expected to be amplified in HER2-positive breast cancers due to their location within the HER2 amplicon on the long arm of chromosome 17 (17q12)." (PMID 33087122, 2020). "Previous reports have identified co-amplification of GRB7, PNMT, and TCAP in HER2-positive breast cancer, specifically due to their location in the 17q12 region." (PMID 33087122, 2020). "In addition, the genes TCAP, PSMD3, GRB7, and ERBB2 from the ERBB2 group are derived from the same well known breast cancer amplicon." (PMID 20158879, 2010).
hypertrophic cardiomyopathy (5 papers, 2019 to 2025). "For example, TCAP (regulates sarcomere assembly and titin assembly; implicated in familial hypertrophic cardiomyopathy), MYL3 (myosin light chain 3; implicated in left ventricular hypertrophic cardiomyopathy and restrictive cardiomyopathy), LDB3, and DES were highly downregulated." (PMID 34338636, 2021). "It has been shown that dysfunctional TCAP within the Z-disc increases the calcium sensitivity via the Calsarcin-1 and calcineurin complex, which is a mediator of hypertrophy and leads to hypertrophic cardiomyopathy." (PMID 31426609, 2019).
limb-girdle muscular dystrophy (5 papers, 2012 to 2024). Limb-girdle muscular dystrophy (LGMD) is a heterogeneous group of muscular dystrophies characterized by proximal weakness affecting the pelvic and shoulder girdles. "On identifying the relevant variants in the CAPN3, DYSF, and TCAP genes, the diagnosis was oriented toward limb-girdle muscular dystrophy (LGMD) in six patients from four families." (PMID 37377599, 2023). "This could lead toZ-disc disorganization and TCAP itself is associated withdestabilization in limb girdle muscular dystrophy 2G." (PMID 22956992, 2012). "Limb-girdle muscular dystrophy (LGMD) is a progressive muscle weakness affecting the pelvic and shoulder girdles, primarily caused by mutations in proteins like myotilin, lamin, caveolin-3, calpain-3, dysferlin, γ-sarcoglycan, TCAP, TRIM32, FKRP, and titin." (PMID 39415830, 2024).
Anxiety (4 papers, 2018 to 2022). Intense feelings of nervousness, tension, or panic often arise in response to interpersonal stresses. "This region corresponds to the teneurin C-terminal associated peptide (TCAP), which is thought to function independently of intact teneurins to stimulate neurite outgrowth, regulate dendritic morphology and modulate anxiety behaviors in rats." (PMID 30930731, 2019). "There is a clear functionality for soluble TCAP in modulating neuronal contacting in culture, which offers a likely cellular-level explanation for its ability to modulates stress- and anxiety-related behaviours in vivo." (PMID 35585927, 2022). "Indeed, Tens and its proteolytic products, such as TCAP and ICD, have been linked with important effects on the adult nervous system, including the management of addiction and anxiety." (PMID 31156379, 2019). "In vivo, TCAP is known to regulate anxiety behaviours of rats." (PMID 29540701, 2018).
heart failure (4 papers, 2014 to 2023). Inability of the heart to pump blood at an adequate rate to meet tissue metabolic requirements. "However, we identified no disease-causing variants in the gene among our cohort suggesting the TCAP gene may not be a common cause of heart failure among Iranian patients." (PMID 37752589, 2023).
muscular dystrophy (3 papers, 2021 to 2025). Muscular dystrophy (MD) refers to a group of more than 30 genetic diseases characterized by progressive weakness and degeneration of the skeletal muscles that control movement. "Consistent implication of MYBPC3, CSRP3, CAV3, TCAP, and TTN across multiple pathways highlights convergent mechanisms, while moderate enrichment of muscular dystrophy pathways (involving CAV3 and TTN) further suggests overlapping pathophysiological networks." (PMID 41153379, 2025).
cardiac hypertrophy (2 papers, 2018 to 2020). "The interaction between MDM2 and TCAP is known to be important for cardiac hypertrophy, it was also shown that TCAP controls secretion of MSTN." (PMID 32928103, 2020).
Hearing impairment (2 papers, 2019 to 2022). A decreased magnitude of the sensory perception of sound. "Tcap (titin-cap) is another candidate gene that is responsible for hearing loss." (PMID 30918314, 2019).
limb-girdle muscular dystrophy type 2G (2 papers, 2014 to 2017). "Note also that muscular dystrophy, limb girdle type 2G is associated in humans with TCAP polymorphism (OMIM#604488) and the histopathology resembles marbling in some respects." (PMID 28913347, 2017).
melanoma (2 papers, 2024 to 2025). A malignant, usually aggressive tumor composed of atypical, neoplastic melanocytes. "Similarly, projection of the PCV and breach TEC markers showed enrichment in rCap in our dataset, 6 h post melanoma injection, whereas tCap markers were expressed by several capillary clusters." (PMID 39627185, 2024). "In GSE46517, IFFO1, ANKRD10, CLPB, TCAP, and POLG2 displayed high expression, but the expression levels of CHMP4A, ZDHHC11, and ANKMY1 were low in the melanoma group." (PMID 40909968, 2025).
diabetes (1 paper, 2025). "A diabetes-specific targeted analysis showed negatively enriched Z-disc and contractile gene sets enriched due to the downregulation of CASQ2, peripherin (PRPH), nebulette (NEBL), titin-cap (TCAP), and LIM domain-binding proteins LDB3, PDLIM4, and PDLIM5 (Dataset EV36)." (PMID 40759793, 2025).
Fanconi anemia (1 paper, 2022). Fanconi anemia (FA) is a hereditary DNA repair disorder characterized by progressive pancytopenia with bone marrow failure, variable congenital malformations and predisposition to develop hematological or solid tumors. "Similar to FBXL21 ubiquitinating MYOZ1 and TCAP, another E3 ligase, the FANCL subunit of the FA (Fanconi anemia) core complex, has been shown to monoubiquitinate two interacting proteins, namely FANCD2 and FANCI." (PMID 36574402, 2022).
leukaemia (1 paper, 2022). "We identified differential methylation of genes that have been related to cancers such as lymphoma (WNT6, TP73, and CD37), leukaemia (MEIS1, HOXA4, and HOXA5) or neuroblastoma (TP73), as well as genes related to cardiovascular diseases (UCN, PRDM16, TCAP, ALOX5)." (PMID 35354948, 2022).
mood disorder (1 paper, 2019). A cognitive disorder a disturbance in which the person's mood is hypothesized to be the main underlying feature. "Thus, taken together, these observations indicated that TCAP and related peptides could play a major role in the treatment of mood disorders including depression, anxiety, and post-traumatic-stress disorder, for example." (PMID 31781029, 2019).
skeletal myopathies (1 paper, 2014). "Telethonin (also known as titin-cap or t-cap) is a muscle-specific protein whose mutation is associated with cardiac and skeletal myopathies through unknown mechanisms." (PMID 24280220, 2014).
cancer (3 papers, 2022 to 2025). A tumor composed of atypical neoplastic, often pleomorphic cells that invade other tissues. "However, the role of genes such as PNMT, TCAP, and PPP1R1B in BC and other cancers is still not well defined, requiring further research to understand their potential as biomarkers or therapeutic targets." (PMID 40136626, 2025).
myopathies (3 papers, 2014 to 2022). "In contrast to severe myopathies due to human TCAP mutations, TCAP knockout led to relatively mild phenotypes under normal conditions in mice, suggesting dysregulation of additional target proteins contributes to the marked muscle dysfunction in Psttm mice." (PMID 36574402, 2022). "A functional role for telethonin has been implicated in sarcomere development and stability, and mutations in TCAP are causally associated with both skeletal and cardiac myopathies." (PMID 24280220, 2014).
tumor (3 papers, 2015 to 2024). "However, rCap markers were also expressed by tumor capillary ECs (tCap) and breach ECs, which are suggested to breach the basal lamina allowing tip ECs to lead vessel growth." (PMID 39627185, 2024). "In almost the same way, aberrant expression of TCAP and BPI was in relation with multiple types of tumor." (PMID 29760609, 2018).
infection (1 paper, 2024). The state of being infected such as from the introduction of a foreign agent such as serum, vaccine, antigenic substance or organism. "TcaP expression results in the formation of small capsids during ICP1 infection, which suggests that it has scaffolding activity." (PMID 38206122, 2024). "Expression of TcaP during ICP1 infection was sufficient to redirect capsid size, but other capsid remodeling satellites have been shown to use either a single protein or two proteins that act in concert to direct small capsid assembly." (PMID 38206122, 2024). "(C, D) Representative TEMs of lysates produced from ICP1 infection of V. cholerae expressing (C) TcaP (ptcaP) or (D) an empty vector (pEV)." (PMID 38206122, 2024). "Importantly, these data demonstrate that tcaP expression during ICP1 infection, in the absence of other PLE-encoded products, results in the production of small capsids." (PMID 38206122, 2024).
TCAP also shares sentences with these, for which no sentence is quoted: gastric cancer (2 papers); autosomal recessive limb-girdle muscular dystrophy (1); Berdon Syndrome (1); Brugada syndrome (1); cardiovascular diseases (1); Chronic Intestinal Pseudo Obstruction (1); cocaine addiction (1); collagenopathies (1); congenital muscular dystrophy (1); Danon disease (1); dermatomyositis (1); Emery-Dreifuss muscular dystrophy (1); familial hypertrophic cardiomyopathy (1); laminopathy (1); lymphoma (1); myocarditis (1); myotilinopathy (1); neuroblastoma (1); Obesity (1); Pompe disease (1); proteinopathy (1); restrictive cardiomyopathy (1); sarcoglycanopathies (1); vacuolar myopathy (1); visceral myopathy (1).